RPL36AP6 (ribosomal protein L36a pseudogene 6)
Synonyms: bA380I20.1
Gene: Processed pseudogene on chromosome 9 (107,834,509 to 107,834,829, reverse strand). Ensembl gene ENSG00000231293.
Diseases named in the same sentence as RPL36AP6 in open-access papers:
RPL36AP6 is named in the same sentence as 1 disease in open-access papers, as found by Europe PMC text mining. Sharing a sentence is not in itself a finding about the gene and the disease.
RPL36AP6 shares sentences with these, for which no sentence is quoted: breast carcinoma (1 paper).